POSTN (periostin)
Diseases named in the same sentence as POSTN in open-access papers (continued):
Sharing a sentence is not in itself a finding about the gene and the disease.
tumor (continued). "In the other study, which also showed POSTN to be far more overexpressed in tumor tissues than in peritumoral tissues, POSTN appeared to be overexpressed both by the epithelial and by the stromal cells." (PMID 23273263, 2012). "It is thought that periostin enhances tumor growth through multiple pathways such as promoting cell proliferation, evasion of apoptosis, limitless replicative potential, genomic instability and induction of angiogenesis." (PMID 21504578, 2011). "It is thought that Periostin stimulates tumor cell growth by preventing apoptosis and promoting angiogenesis and enhances the survival of tumor cells via the Akt/PKB pathway." (PMID 21714934, 2011). "But, the tumor cells of the tissues of 6 xenografts from the group of down-regulated Periostin LNCap cells showed weak positive Periostin expression." (PMID 21714934, 2011). "It is indicated that periostin can facilitate tumor invasion and metastasis by the process of epithelial-mesenchymal transition(EMT) which enables epithelial cancer cells to acquire invasive and metastatic potential." (PMID 21504578, 2011). "Periostin overexpression in human tumors can enhance tumor growth and always increase tumor invasion and metastasis." (PMID 21714934, 2011). "Immunohistochemical staining was performed to evaluate Periostin expression in the stromal or tumor cells of the xenografts." (PMID 21714934, 2011). "Univariate Cox analysis further highlighted genes whose expression was most strongly associated with patient survival including, POSTN and RUNX1 that were found to be common to the stromal reaction of both tumor types." (PMID 21611158, 2011). "Binding of periostin to αVβ3, αVβ5 or α6β4 integrins has been reported to promote invasion of tumor cells by enhancing cell survival via the Akt/PKB pathway." (PMID 21611158, 2011). "Suggested effects of periostin on tumour cells include increased growth and resistance against hypoxia and chemotherapeutics." (PMID 20534149, 2010). "The presence of both mRNA and protein in the cytoplasm of tumour cells favours an active or signal transducting role of periostin, respectively." (PMID 20534149, 2010). "It has been concluded that its expression characteristics and cancer specific up-regulation make periostin a promising target for ligand-based tumour targeting strategies." (PMID 20534149, 2010). "Meanwhile, periostin has been found up-regulated in several tumour entities, either in the stroma, the epithelial cells or in the serum." (PMID 20534149, 2010). "The aim of our study was to determine the periostin expression in the stromal and epithelial compartment of the tumour, as well as the correlation with clinical data including patient follow up data in a larger cohort." (PMID 20534149, 2010). "In the tumor epithelium, there were only three genes (POSTN, periostin; SPARC, osteoconectin; SPARCL1, SPARC-like 1) that were significantly upregulated in IDC relative to DCIS." (PMID 19187537, 2009). "In this study, we used quantitative RT-PCR to assess periostin gene expression in normal tissues, primary cell cultures, tumor tissues and tumor cell lines." (PMID 18086302, 2007). "Although POSTN overexpression does not seem to be systematic in human tumors, studies agree on the low level of periostin expression in most tumor cell lines." (PMID 18086302, 2007). "By comparison, cell line/tumor ratio of POSTN expression was smaller than 1% in only six cases; the ratio was comprised between 5 and 8% in three cases and higher than 25% in LB2077-1, LB2077-4 and LB2730-1." (PMID 18086302, 2007). "Strikingly, our analysis revealed a significant increase of POSTN expression in more than 60% of tumor-invaded lymph nodes (P = 0.003)." (PMID 18086302, 2007). "Lower levels of POSTN expression in tumor cell lines compared to tumor tissues are in agreement with studies showing a production of periostin by stromal cells -and not cancer cells- in tumors." (PMID 18086302, 2007).
tumor (continued). "Clinical studies of periostin expression in human cancers have demonstrated that increased expression of POSTN is correlated with tumour angiogenesis and metastasis." (PMID 17014703, 2006). "However, it should be noted that in each tumour type, including LCTs, a significant correlation was observed between the expression of POSTN and PDPN and the number of positive cells and/or the intensity of the reaction." (PMID 41361308, 2025). "We compared GSN expression to adjacent sections of tumour stained for POSTN, α-SMA, CD3 and EpCAM." (PMID 40640495, 2025). "To assess whether POSTN-driven EMT enhances tumor aggressiveness, we evaluated its impact on cell migration and invasion." (PMID 40520021, 2025). "Furthermore, infiltrating tumor cells, in turn, stimulate fibroblasts of secondary target organs to express periostin, a component of the stromal extracellular matrix that promotes colonization by tumor cells." (PMID 40649909, 2025). "Furthermore, targeting the POSTN-NOTCH1 signaling axis proves effective in suppressing SCLC tumor growth and inhibiting liver metastasis." (PMID 39762921, 2025). "The same tumours were also immunohistochemically positive for both POSTN and PDPN." (PMID 41361308, 2025). "In vitro experiments demonstrated that POSTN silencing could inhibit tumor cell proliferation and invasion." (PMID 40991535, 2025). "High POSTN levels enhance SCLC tumor cell proliferation and metastatic dissemination." (PMID 39762921, 2025). "Spatial validation through immunofluorescence in tissue sections from four patients in the PUCH-PDAC cohort showed significant co-localization of POSTN and integrin β5 on tumor cell membranes, providing in situ evidence for the functional relevance of the POSTN-ITGAV/ITGB5 axis in PDAC." (PMID 40520021, 2025). "In addition, CRC with periostin-positive expression in tumor stromal cells was significantly correlated with lymph node metastasis, venous invasion, and a high relapse rate." (PMID 39941916, 2025). "The mechanism underlying POSTN-mediated recurrence may involve its regulation of epithelial-mesenchymal transition (EMT), a key process driving tumor invasion and metastasis." (PMID 40991535, 2025). "Proteogenomics unveiled tumour environment during LNM dissemination may be fostered by elevated POSTN, potentially inducing ECM reorganisation that interacts with TGF‐β and disrupts cell cycle regulation to suppress the immune response." (PMID 40038875, 2025). "Periostin is not normally produced by esophageal epithelial cells, but rather by activated fibroblasts in the tumor stroma (i.e., cancer-associated fibroblasts, CAFs)." (PMID 40872572, 2025). "Several CAF IHC biomarkers, particularly CD163, MMP-9, periostin, and vimentin, significantly associated with prognosis in CRC, could be proposed as surrogates for the phenotypical characterization of the tumor microenvironment." (PMID 41450913, 2025). "HCC patients with more POSTN+ CAFs had shorter overall survival and progression-free survival, indicating that POSTN+ CAFs may promote tumor progression and adversely affect patient prognosis." (PMID 41018265, 2025). "In the TME of OC, periostin (POSTN), a protein associated with hyperplasia of the osteoclasts, is highly expressed and facilitates the recruitment of macrophages via TGF-β, creating a positive feedback loop conducive to tumor development." (PMID 40369674, 2025). "Pharmacological agents that inhibit the expression or secretion of POSTN by tumor cells or stromal cells may reduce HCC progression." (PMID 41018265, 2025). "Inducing POSTN knockdown with Doxycycline treatment at a tumor size of 30 mm2 resulted in a significantly reduced tumor growth rate, evidenced by smaller tumor volumes and lighter tumor weights." (PMID 39762921, 2025). "The tumor microenvironment may also be influenced by the regulation of tumor-associated macrophages (through LTBP-1 and POSTN)." (PMID 40143207, 2025).
tumor (continued). "However, existing studies have shown that soluble POSTN secreted by CAFs in the tumor microenvironment can paracrinally activate adjacent tumor cells through integrin αVβ3, driving EMT and promoting metastasis." (PMID 40991535, 2025). "Elevated POSTN in the tumor microenvironment has been documented in both subtypes." (PMID 40872572, 2025). "In addition, tumor cells can also promote HSC activation into CAF (including POSTN+ CAFs), and the bidirectional interaction between them forms a positive feedback loop to promote tumor growth, invasion and metastasis." (PMID 41018265, 2025). "This tumour microenvironment may be driven by augmented POSTN, ECM remodelling, TGF‐β pathway activation, and cell cycle control disruption." (PMID 40038875, 2025). "POSTN was highly expressed in epithelial cells and tumor stroma of HCC." (PMID 41018265, 2025). "Downregulation of AEBP1 in tumour endothelial cells in vitro reduced levels of angiogenesis-related genes, POSTN and AQP1, suggesting that AEBP1 may regulate new blood vessel formation." (PMID 39930483, 2025). "Inhibition of IL-6 or its downstream pathways, including STAT3, could inhibit POSTN secretion and reduce tumor aggressiveness." (PMID 40426238, 2025). "Emerging evidence supports that POSTN promotes EMT to enhance the motility of tumor cells." (PMID 40991535, 2025). "The ideal therapeutic strategy may require targeting both tumor cells and CAFs simultaneously, such as combining POSTN siRNA and FAP inhibitors." (PMID 41018265, 2025). "In contrast, tumor-associated ECs predominantly expressed pro-angiogenic and extracellular matrix remodeling genes, including Heparan Sulfate Proteoglycan 2 (HSPG2) and Periostin (POSTN)." (PMID 40599812, 2025). "Interestingly, in our study, we revealed that POSTN expression supports an immunosuppressive tumor microenvironment and reduced T cell infiltration." (PMID 38389400, 2024). "Notably, this FAP+ POSTN+ CAF(c01_CST1) is significantly enriched in the tumor side, while myofibroblasts (c03_MYH11) show less proportion in this area." (PMID 39716897, 2024). "Notably, these CD146+ vCAFs were predominantly located in the tumor core, while other CAFs expressing POSTN were localized in the invasive tumor front." (PMID 38453816, 2024). "Some components of the ECM, such as periostin, can induce tumor cell growth in macrometastasis." (PMID 39682261, 2024). "Therefore, IL-4-STAT6 signaling contributes to POSTN expression in activated CAFs, whereas POSTN-integrin-FAK-STAT3 signaling promotes IL-4 expression in tumor cells during papillary thyroid tumor tumorigenesis." (PMID 38773979, 2024). "Compared with previous studies, the novelty of this study is that circ‐POSTN knockdown might repress EC tumor growth and improve radiosensitivity in vivo." (PMID 38553795, 2024). "Moreover, POSTN-OE tumor cells exhibited increased proliferative potential in comparison to control cells." (PMID 38773979, 2024). "Additionally, periostin can significantly protect PCCs from gemcitabine-induced DNA damage, enhance the resistance of PCCs to gemcitabine, and inhibit tumor cell apoptosis." (PMID 38706910, 2024). "Moreover, the expression of POSTN correlates with tumor size, stage of the disease, invasion of lymph nodes by tumor cells, metastasis, and tumor recurrence." (PMID 39329988, 2024). "Furthermore, western blot and qRT-PCR assays revealed that FAK inhibitor PF573228 efficiently down-regulated p-STAT3 and IL-4 levels and the STAT3 inhibitor Stattic inhibited the POSTN-induced IL-4 upregulation in tumor cells." (PMID 38773979, 2024). "We found that the interaction of POSTN+ fibroblasts with SPP1+ macrophages, POSTN+ fibroblasts with tumor cells, and SPP1+ macrophages with tumor cells gradually increased from NT to Pre, E and A stages, which was also observed in separate analyses in P2, P10, and P13." (PMID 38519500, 2024).
tumor (continued). "Additionally, we found that FYN expression in xenograft tumor tissues that were exposed to IR treatment had no significant change compared to the sh‐NC group, while it was obviously decreased in xenograft tumor tissues with sh‐circ‐POSTN treatment." (PMID 38553795, 2024). "Additionally, high levels of POSTN expression in tumor cells and tumor stroma correlated with the presence of single metastases to regional lymph nodes (pN1; * p < 0.05)." (PMID 39272978, 2024). "Further, POSTN is involved in tumor microenvironment remodeling during tumor progression." (PMID 38389400, 2024). "A high expression of POSTN in tumor cells and tumor stroma may act as an independent prognostic factor in patients with NSCLC and in relation to its histological subtypes (namely SCC and AC)." (PMID 39272978, 2024). "In addition, circ‐POSTN silence curbed tumor growth and strengthened radiosensitivity in EC in vivo." (PMID 38553795, 2024). "CD70- and/or POSTN-positive CAFs may have limited capacity for the modulation of the tumor immune microenvironment." (PMID 38473788, 2024). "This may be attributed to the immunosuppressive tumor microenvironment and reduced T cell infiltration by POSTN expression." (PMID 38389400, 2024). "The GSEA analysis revealed that POSTN expression was positively correlated with chemotaxis and cell migration, indicating that elevated POSTN expression may modulate the tumor immune microenvironment." (PMID 38389400, 2024). "Moreover, POSTN expression exhibited a positive correlation with advanced tumor stages, and patients with high POSTN expression had a reduced overall survival." (PMID 38773979, 2024). "In addition, this study found that POSTN expression (in tumor cells/CAFs) increased with tumor size (pT), histopathological grade (G), and lymph-node involvement (pN)." (PMID 39272978, 2024). "All of these findings indicated that cardiac remodeling from various models could increase tumor growth and metastasis, which could be due to the secretion of factors including periostin, FN and CTGF." (PMID 38279150, 2024). "Moreover, silencing of POSTN in xenografts specifically attenuated the tumor-supportive M2 type of TAMs that promote tumor progression and counteract the antitumor effects of T lymphocytes." (PMID 38347567, 2024). "In patients with advanced NSCLC, POSTN accumulates in the cytoplasm of tumor cells, suggesting the existence of non-canonical biological effects of POSTN associated with tumorigenesis." (PMID 39329988, 2024). "Thus, distinct cell types within a tumor can apparently act as a source for POSTN and MDK, raising the question about the identity of their effector cells." (PMID 38942020, 2024). "POSTN, also known as osteoblast-specific factor, is a multifunctional matricellular protein initially identified in osteoblasts; it plays a significant role in regulating inflammatory responses and the tumor microenvironment (TME)." (PMID 39001398, 2024). "However, other HGs, especially collagen‐related genes, including COL1A1, COL1A2, ITGA2, and POSTN revealed slightly higher methylation in tumor tissue than in normal tissue." (PMID 38639039, 2024). "Importantly, we found that CAFs overexpressing FN1 and POSTN significantly promoted the wound healing and invasion ability of tumor cells in vitro validation." (PMID 38601538, 2024). "In addition, the results showed an increasing level of POSTN expression in both tumor cells and tumor stroma with an increase in the histological grade (G)." (PMID 39272978, 2024). "By targeting POSTN and modulating the immune tumor microenvironment, we may pave the way for more effective and personalized treatment strategies in this aggressive malignancy." (PMID 38389400, 2024). "This indicates that POSTN may play an important role in the adaptation of tumors to hypoxic conditions, which is important for further tumor growth and disease development." (PMID 39272978, 2024).
tumor (continued). "Nevertheless, genetic ablation of CAF-derived POSTN has demonstrated accelerated tumor growth because it is essential for the formation of tumor capsules, indicating that certain POSTN+ CAFs may be protective against tumor progression." (PMID 39107856, 2024). "Likewise, fast-progressing tumors displayed more prominent POSTN (also termed periostin) protein expression than slow-progressing tumors, as shown by immunohistochemical staining of tumor sections." (PMID 38942020, 2024). "Therefore, the aim of this study was to analyze the correlation of pro-angiogenic factors with POSTN expression (in cancer cells and tumor stroma) in individual histological subtypes of NSCLC." (PMID 39272978, 2024). "We confirmed that POSTN is expressed almost exclusively in tumor cells." (PMID 39227950, 2024). "This intriguing connection led us to explore the potential cytokines from tumor cells that might be responsible for driving CAF-derived POSTN-induced progression of papillary thyroid tumors." (PMID 38773979, 2024). "Circ‐POSTN interference also suppressed tumor growth and enhanced radiosensitivity in vivo." (PMID 38553795, 2024). "Our study has demonstrated a significant association between soluble POSTN levels and both tumor volume and TNM stages in BCa patients without distant metastasis." (PMID 38504252, 2024). "Moreover, POSTN plays a pivotal role in the remodeling of various tumor microenvironments, including the cancer stem cell niche, the perivascular niche, the premetastatic niche, and the immunosuppressive microenvironment." (PMID 39195230, 2024). "However, there was selective expansion of the POSTN+ fibroblasts which were present adjacent to the tumour islands." (PMID 38165934, 2024). "POSTN causes the stimulation of CD163 + macrophages to produce several cytokines including Treg-associated chemokines [chemokine ligand 17 (CCL17), CCL22] which in turn induce the recruitment of Tregs to the tumor site in melanoma." (PMID 39003350, 2024). "As a result, levels of soluble POSTN may provide a more accurate real-time snapshot of tumor burden." (PMID 38504252, 2024). "Periostin is involved in the initiation of the tumor microenvironment." (PMID 36598904, 2023). "Accumulated evidence suggested that POSTN promotes tumor metastasis by regulating immune responses." (PMID 36611136, 2023). "Periostin (POSTN) is an extracellular matrix protein, and its main functions are induction of fibrillogenesis, fibroblastic cell proliferation and migration, enhancing regeneration in normal tissue, and promoting metastasis in case of neoplasia." (PMID 38076555, 2023). "Based on our previous study, we hypothesized that tumor promotion following cardiac remodeling is dependent on Periostin expression." (PMID 38139195, 2023). "Additional proliferative signaling may induce reawakening through the induction of periostin in metastatic niche fibroblasts by tumor cells, which in turn activates tumor-initiating cells and remodels the ECM with aging and inflammation." (PMID 37296983, 2023). "Previous literature dealing with other tumor contexts highlighted the ability of TnC, POSTN, and OPN to regulate several core roles, which orchestrate tumorigenesis and tumor progression, such as proliferation, cell viability, migration, angiogenesis, pro-invasive pathways, and stemness induction." (PMID 36902188, 2023). "Recent evidence revealed that POSTN could recruit M2 tumor-related macrophages and promote malignant growth." (PMID 36611136, 2023). "Notably, mCAFs highly expressed tumor invasion-associated genes (FAP, MMP1, MMP14, and POSTN), commonly associated with ECM remodeling and cell migration during tumor metastasis, thus reflecting the importance of mCAFs in the metastatic TME." (PMID 37853464, 2023). "Interestingly, POSTN+ CAFs (C02_POSTN) were identified at substantial amount in multiple mBrain samples, corresponding to the function of periostin in promoting tumour metastasis." (PMID 38115703, 2023).